MET (MET proto-oncogene, receptor tyrosine kinase)
Diseases named in the same sentence as MET in open-access papers (continued):
Sharing a sentence is not in itself a finding about the gene and the disease.
tumor (continued). "Cabozantinib is a multitargeted TKI that inhibits VEGFR, MET, and AXL pathways, which are vital for tumour progression and angiogenesis but also play critical roles in maintaining normal liver function." (PMID 40957947, 2025). "This fusion-driven pathway is critical for tumour growth, as EWSR1-ATF1 is essential for c-MET expression, and malignant proliferation in these tumours appears to be dependent on c-MET signalling." (PMID 41020828, 2025). "Bypass signaling activation involves the upregulation of alternative pathways, such as MET, HER2, and RAS-MAPK, which allow tumor cells to sustain proliferation despite EGFR inhibition." (PMID 40076686, 2025). "MET is the hepatocyte growth factor (HGF) receptor and its expression is dysregulated in several tumours." (PMID 40332222, 2025). "The involvement of MET in GBM, marked by overexpression, amplification, and activating alterations, underscores its importance in tumor biology." (PMID 40332008, 2025). "Circulating tumor cells (CTCs) were detected through the expression of epithelial markers (EPCAM, EGFR, and MET)." (PMID 40616388, 2025). "MET, a receptor tyrosine kinase (RTK), plays a critical role in tumor growth, invasion, and metastasis." (PMID 40386554, 2025). "In combination therapy of a TKI and ICI, the TKI has been shown to enhance the tumor-suppressive effect of the ICI by inhibiting the immunosuppressive roles of vascular endothelial growth factor receptor (VEGFR) and MET." (PMID 40004241, 2025). "The CD44v6 isoform forms a trimeric complex with MET and hepatocyte growth factor, activating RAS-MAPK, PI3K/Akt, and MET transcription pathways, contributing to chemoresistance and tumor progression." (PMID 40363706, 2025). "We further examined the level of c-MET and NCL in tumor tissues and observed that AS1411-SL1-2 effectively degraded c-MET while leaving NCL level unaffected." (PMID 39744222, 2025). "MET, a receptor tyrosine kinase (RTK), is activated by ligands such as hepatocyte growth factor (HGF)/scattering factor (SF) and drives key processes in tumor progression, including invasion, proliferation, and angiogenesis." (PMID 40673866, 2025). "Conclusions: c-MET and CEA emerged as optimal tumor imaging targets, showing sustained differential expression after nCRT." (PMID 40563608, 2025). "Although our proteomics study revealed MET phosphorylation and activation of the downstream signaling pathways in the resected tumor sample, this activation cannot be directly attributed to the R970C mutation as it was not confirmed in the resected tumor specimen." (PMID 40386554, 2025). "MET overexpression (IHC 3+) found in ≥90% of tumor cells and/or MET copy number ≥10 (fluorescence in situ hybridization—FISH) were used to identify the high MET-expressing group (34% of the population)." (PMID 40361442, 2025). "In the trial a PR was observed in a c-MET amplified NSCLC, a prolonged SD with 20% tumor shrinkage in a HER2 mutant NSCLC, and prolonged SD responses in multiple other tumor types, including the almost untreatable disease, uveal melanoma." (PMID 38441437, 2024). "It suppresses tumor growth by interfering with ligand–receptor interactions and blocking ligand-induced phosphorylation of EGFR and c-MET." (PMID 38892105, 2024). "Crizotinib, a multi-target protease inhibitor, is commonly used in tumor patients with abnormal AKL, ROS, and MET kinase activities." (PMID 38472489, 2024). "TAM+/TIL+ tumors featured activation of MET and STAT3 signaling, increased stress response, tumor inflammation, senescence and activation of microglia and astrocytes but also activated interferon signaling." (PMID 38386085, 2024). "As these cells inhibit the proliferation of anti-tumor lymphocytes and expand Treg, the HGF/MET axis significantly contributes to immunosuppression." (PMID 38892318, 2024).
tumor (continued). "c-MET can trigger various downstream pathways, including the RAS/MAPK and phosphoinositide 3-kinase (PI3K)/AKT pathways, promoting tumor cell proliferation, growth and metastasis in HCC." (PMID 39569202, 2024). "The newly developed BsAb BS001 was designed to bind c-MET and CD3, demonstrating potent T cell mediated killing of tumor cells in vitro." (PMID 39664377, 2024). "In HNSCC PDX tumor, a subcluster with high expression of EGFR simultaneously had elevated level of MET." (PMID 38916448, 2024). "Preclinical studies demonstrate that dual inhibition of c-MET and TGF-β pathways synergistically reduces tumor growth, metastasis, and immune evasion, highlighting the potential of this approach." (PMID 39664377, 2024). "The HGF/c-MET pathway also regulates epithelial–mesenchymal transition (EMT) in NSCLC, an important process that enhances tumor cell migration and invasion, and serves as an adaptive drug resistance mechanism." (PMID 39201787, 2024). "Amivantamab is a bispecific monoclonal antibody that prevents tumor growth and progression by blocking EGFR and c-MET pathways and stimulates immune-mediated destruction of EGFR and cMET-expressing cells." (PMID 38605928, 2024). "Accordingly, developing a BsAb targeting both c-MET and CD137 aimed to optimize the BsAb format and CD137 binder to ensure efficient delivery of the CD137 agonist to the tumor microenvironment." (PMID 39664377, 2024). "Lastly, if MET is gained but ERBB2 is lost, the tumor has a greater than 90% chance of being from the small bowel." (PMID 39062773, 2024). "The secondary specificity of c-MET BsAbs, targeted at immune cell receptors such as CD3 or PD-1, is intended to use the cytotoxic capabilities of immune cells against tumor cells." (PMID 39664377, 2024). "We subsequently analyzed the single-cell transcriptomic landscape of the tumor and revealed that tumor cells exhibited relatively high EGFR and MET expression in response to pembrolizumab treatment alone." (PMID 38916448, 2024). "Targeting MET alongside VEGF inhibition with the small-molecule kinase inhibitor, cabozantinib, can reduce tumor aggressiveness in pre-clinical pancreatic and neuroblastoma cancers." (PMID 39769452, 2024). "An examination of mRNA levels within the TCGA-GTEx cohort demonstrated a notable increase in KLK10, LAMA3, MET, KRT7, and SFTA2, alongside a decrease in MT1X in tumor samples compared to their normal counterparts." (PMID 38893622, 2024). "The MET protein is a receptor tyrosine kinase which upon binding its ligand, hepatocyte growth factor (HGF), mediates tumor cell proliferation, epithelial-mesenchymal transition (EMT), motility, invasion, angiogenesis and metastasis." (PMID 38485737, 2024). "While our PDXs showed similar heterogeneity in MET pathway activation as the patient tissues from which they were derived, the PDX were generated from independent tumor areas." (PMID 38276867, 2024). "Short-term response to MET inhibitors observed in multiple clinical trials as well as dis-concordant efficacy of immunotherapy leads to the following hypothesis: there is an inter-patient/tumor heterogeneity with clinical and biological significance in patients with METex14 NSCLC21." (PMID 39060379, 2024). "The tumour cells at the tip of the papillae and stromal invasion were more intensely and frequently stained for CD24 and MET." (PMID 38030594, 2024). "Accordingly, concurrent MET and VEGF targeting mitigates tumor aggressiveness in pancreatic carcinoma." (PMID 38675409, 2024). "Here, the authors show that co-activation of HGF/MET and Wnt/β-catenin signaling in mouse prostates results in DNPC-like tumor lesions with elevated expression of XPO1 and ribosomal proteins." (PMID 38336745, 2024). "The constitutive activation of receptor tyrosine kinases (RTKs) such as ALK, MET, and VEGFR is known to promote tumor progression in ARMS, by reprogramming many intracellular pathways, such as those involved in differentiation." (PMID 38474036, 2024).
tumor (continued). "CD44v6, as a tumor marker in the CD44 family, forms a trimeric complex with MET and HGF to promote MET activation and activate three downstream pathways: RAS-MAPK activation, PI3K/Akt promotion, and MET transcription enhancement." (PMID 38736891, 2024). "To obtain an overview of which checkpoint ligands are expressed on HNSCC tumor cells and if these ligands are affected by HGF/MET signaling, we used mRNA sequencing and antibody-based techniques for identifying checkpoint ligands in six HNSCC tumor cell lines." (PMID 39000441, 2024). "The inhibition of c-MET, such as through TMZ administration, reduces vascular formation and tumor growth." (PMID 38892305, 2024). "In instances of HGF-dependent c-MET activation, emibetuzumab obstructs HGF binding to c-MET, inhibiting c-MET phosphorylation and subsequent tumor growth suppression in both in vitro and in vivo settings." (PMID 39664377, 2024). "ADCT, consisting of the tumor-targeted, antibody-mediated transfer of membrane fragments from tumor cells to effector cells, significantly contributes to the removal of both EGFR and MET from the cancer cell surface." (PMID 38892318, 2024). "JNJ-61186372 exhibited anti-tumor effects in wild-type and mutant EGFR and c-MET pathway activation scenarios." (PMID 39664377, 2024). "Inflammation activates oncogenic signaling pathways including NF-κB, MET, STAT3, mTOR and MAPK, leading to tumor progression and an aggressive phenotype." (PMID 38561856, 2024). "Single-cell RNA transcriptomic analysis showed that pembrolizumab alone induced tumor invasive mechanism by upregulation of EGFR and MET signaling." (PMID 38916448, 2024). "The hyperactivity of c-MET and HGF contributes to tumor progression, metastasis, and invasion in various cancers and correlates with advanced cancer stages, poor overall patient survival rate, and prognosis." (PMID 39458991, 2024). "This suggested that a large proportion of the tumor actively upregulated the expression of EGFR and MET in one of multifaceted responses to pembrolizumab." (PMID 38916448, 2024). "Dual targeting of both MET and VEGFR2 has proven effective in reducing tumor size in a xenograft model." (PMID 38596618, 2024). "In more than 70% of cases, tumour cells showed modified scores of 1 or 2 for CD24 and MET expression, indicating their inhomogeneous expression." (PMID 38030594, 2024). "The stemness of tumor cells can be assessed using multiple methods, such as expression of CD44, MET, OCT4 etc.." (PMID 38600440, 2024). "MET, a receptor tyrosine kinase (RTK), displays in a broad panel of cancers many deregulations liable to promote tumour progression." (PMID 38652103, 2024). "The tumor subcluster expressing high levels of both EGFR and MET (EMHIGH) was define and analyzed for top 50 genes to identify differentially expressed genes (DEGs) in EGFRHIGH/METHIGH and EGFRLOW/METLOW tumor subclusters." (PMID 38916448, 2024). "likewise, IHC staing affirmed that the protein expression patterns of LY6D, MET, MUC16, and WNT7A were increased in tumor sample compared to healthy samples." (PMID 38169540, 2024). "Subsequent NGS of tumor RNA identified a TRIM24::MET fusion between exon 12 of TRIM24 and exon 15 of MET on chromosome 7 involving the MET tyrosine kinase domain." (PMID 38902810, 2024). "In this study, glycovariants of stemness-related biomarker candidates OCT4, MET, CIP2A and LIMA1 were screened from two HNSCC cell lines and, further, from a panel of 25 HNSCC patients using samples of tumor tissue, adjacent normal tissue, and serum samples." (PMID 38600440, 2024). "MET and HGF expression have been reported in various NB cell lines, and HGF-mediated cell invasion and angiogenesis were observed in NB tumor models." (PMID 39458991, 2024). "The inconsistent specimens mainly manifested in the MET and HER2 genes, mainly due to low tumor cellularity, which made accurate interpretation impossible." (PMID 38902688, 2024).
tumor (continued). "Recent research in cancer has identified a link between MET and RON and the development of pro-tumor metabolism." (PMID 39062731, 2024). "The ability of this BsAb to inhibit the migration of c-MET/PD-L1+ CRC cells and exhibit robust anti-tumor effects against HCT116 tumors in mice was demonstrated, possibly by inducing the degradation of c-MET protein in a dose and time-dependent manner." (PMID 39664377, 2024). "The small-molecule inhibitor cabozantinib inhibits the activity of multiple receptor tyrosine kinases, including MET and vascular endothelial growth factor receptor (VEGFR), resulting in the inhibition of tumour angiogenesis and metastasis." (PMID 38204489, 2024). "When combined with gefitinib, a small-molecule EGFR inhibitor, TAK-701 effectively suppresses the phosphorylation of both c-MET and EGFR, along with their downstream signaling pathways, in HCC827-HGF tumor cells." (PMID 39664377, 2024). "Mechanistically, c-MET amplification triggers PD-L1 expression through the PI3K/Akt and MAPK signaling pathways, leading to tumor immune evasion." (PMID 39201787, 2024). "c-MET or amplified MET cell lines and PDX models show substantial tumor growth inhibition and regressions." (PMID 39664377, 2024). "These M2 TAMs secrete HGF, thereby activating the HGF/MET/ERK and PI3K/AKT pathways in the tumor cells and thus facilitating sorafenib resistance." (PMID 39682130, 2024). "Regarding tumor immunity, HGF/MET signaling converts M1 macrophages to M2‐like phenotypes, with M2 macrophages promoting HNSCC cell growth." (PMID 39170944, 2024). "Recent advancements have been made in MET chimeric antigen receptor (CAR) T-cell immunotherapy, which involves modifying a patient’s own T-cells to better target and eliminate tumor cells." (PMID 39201787, 2024). "CDCP1 physically interacts with MET, particularly in contexts like squamous cell carcinoma, where this interaction contributes to resistance to EGFR inhibitors and promotes tumor growth, metastasis, and therapy resistance." (PMID 39769452, 2024). "To understand the regulatory role of HGF/MET and Wnt/β-catenin signaling pathways in promoting DNPC-like tumor development, we assessed the transcriptomics of PCa cells from TripleTg mice." (PMID 38336745, 2024). "MET mutants are related to tumor formation and metastasis in many kinds of cancers, and NPS-1034 inhibits not only wild-type MET but also many MET mutants." (PMID 39000029, 2024). "Pancreatic stellate cells (PSCs), which interact with cancer cells, drive tumor growth and metastasis through the HGF/c-MET pathway." (PMID 39664377, 2024). "This drug demonstrates promising potential in inhibiting c-MET and ALK phosphorylation, curbing tumor cell growth, exhibiting antiangiogenic properties, and inducing apoptosis in specific cancer cells." (PMID 38397899, 2024). "BPI-9016M is a novel small-molecule TKI targeting both c-MET and AXL developed by Betta Pharmaceuticals Co., Ltd, Hangzhou, China., which can suppress tumor cell growth, migration and invasion of lung adenocarcinoma." (PMID 37041472, 2023). "While EGFR kinase inhibitors (EGFR–TKIs) are widely used and efficacious in treatment, increases in resistance and tumor recurrence with alternative survival pathway activation, such as that of AXL and MET, occur frequently." (PMID 37834326, 2023). "HGF secreted in response to CAF irradiation can enhance the phosphorylation activity of c-MET and MAPK in tumor cells, which translates into stronger invasion capacity." (PMID 37607935, 2023). "BPI-9016M is a novel small-molecule TKI that targets both c-MET and AXL, which inhibits tumor cell growth, migration and invasion in NSCLC." (PMID 37041472, 2023). "This candidate HGF variant was characterized and evaluated for its ability to mediate c-MET activation and regulate PDX GBM cell growth, motility and invasive potential in vitro and tumor burden in intracranial xenografts in mice." (PMID 37162666, 2023).
tumor (continued). "The differential mRNA expression analysis of genes included in the AVENIO surveillance panel demonstrated that MET, EGFR, SLPI, and TNFRSF21 had the highest difference in log2(TPM + 1) between NSCLC tumours and PBMCs." (PMID 36825535, 2023). "A recent phase Ib study (NCT02099058) investigated an anti-c-MET directed antibody-drug conjugate (telisotuzumab vedotin) in combination with nivolumab in advanced NSCLC patients and showed limited anti-tumor activity." (PMID 37620318, 2023). "STAT3 is a downstream effector of c-MET/EGFR and is activated in CSCs and primarily expressed in the invasive tumor margin." (PMID 37924112, 2023). "The MET/HGF pathway also positively regulates cancer stem cell enrichment and tumour aggressiveness due to stem cell-related resistance to therapy." (PMID 37514101, 2023). "The MET/HGF pathway can also regulate VEGF expression and promote angiogenesis during tumor progression." (PMID 36831657, 2023). "Hepatocyte growth factor (HGF) is a cytokine secreted by stromal cells in the tumor microenvironment and binds to “mesenchymal-epithelial transition (c-MET) factor,” which is a proto-oncogenic receptor and activates the HGF/c-MET signaling pathway." (PMID 36789987, 2023). "Dysregulation of the MET/HGF pathway leads to uncontrolled cell proliferation and oncogenesis, and is observed in multiple tumor types." (PMID 37681908, 2023). "Some of these oncogenes are paradigms of certain tumor types, as is the case of the amplification of EGFR/ErbB in breast cancer or MET overexpression in non-small cell lung cancer (NSCLC)." (PMID 36839989, 2023). "FISH results from these three cases were reviewed and stated as highly heterogeneous by FISH with focal MET amplifications, partially explaining the results observed by NGS, which is based on a bulk tumor analysis." (PMID 37927472, 2023). "Single-cell analysis further revealed that MET, MUC16, and KRT7 were mainly expressed in cancer cells in PC tumour microenvironment." (PMID 37815881, 2023). "Crizotinib has been confirmed in tumor patients with abnormal ALK, ROS kinase, and HGFR/c‐MET activities." (PMID 37143582, 2023). "The mesenchymal-epithelial transition factor (c-MET or MET) and hepatocyte growth factor (HGF) signaling pathways play crucial roles in tumor development, survival, metastasis, and acquired treatment resistance." (PMID 37692610, 2023). "Several studies have reported that c-MET is overexpressed in ASPS, and MET inhibitors exert anti-tumour activity in ASPS." (PMID 37546405, 2023). "This allows for comprehensive therapy recommendations such as concomitant HER2/MET-amplifications as a potential primary resistance mechanism and MET and BRAF fusions that cannot be as easily assessed in the thoracic tumour board." (PMID 36572733, 2023). "TAS-115 is an oral multikinase inhibitor targeting the MET proto-oncogene, VEGFR, and colony-stimulating factor 1 receptor, which helps to inhibit the tumor growth and the osteoclast differentiation." (PMID 37377920, 2023). "We found that HGF (produced by fibroblasts) induced entrectinib resistance in tumor cells with NTRK1 or ROS1 rearrangement and that HGF‐induced resistance was reversed by combination with HGF/MET inhibitors." (PMID 36416133, 2023). "In this context, we selected the tumor types that also showed a moderate or high correlation between EGFR, MET and PD-L1." (PMID 37370859, 2023). "From a cohort of NSCLC patients previously identified to harbour MET exon 14 skipping alterations, further molecular analyses were performed with residual FFPE tumour samples from 18 patients." (PMID 36799689, 2023). "Overexpression of HGF and/or MET in brain-tumor-derived cells enhances their tumorigenicity and growth, and inhibition of HGF or Met in experimental tumor xenografts suppresses tumor growth and angiogenesis." (PMID 36672409, 2023).